ZNF358 (zinc finger protein 358)
Description:
May be involved in transcriptional regulation.
Synonyms: FLJ10390; ZFEND
Tractability: PROTAC: ubiquitination databases record sites on it.
Gene: Protein-coding gene on chromosome 19 (7,515,292 to 7,521,027, forward strand). Ensembl gene ENSG00000198816.
Subcellular location: Nucleus
Subcellular location (Human Protein Atlas): Nucleoplasm
Gene Ontology:
Molecular function: DNA-binding transcription factor activity; RNA polymerase II cis-regulatory region sequence-specific DNA binding
Biological process: embryonic forelimb morphogenesis; neural tube development; regulation of transcription by RNA polymerase II; stem cell population maintenance
Cellular component: nucleus
Genetic constraint (gnomAD): Loss-of-function variants: 1 observed, 2.21 expected, observed/expected ratio (o/e) 0.45, 90% interval 0.15 to 1.69. That is too few expected variants to judge how well the gene tolerates losing a copy. Missense variants: 550 observed, 638.01 expected, observed/expected ratio (o/e) 0.86, 90% interval 0.8 to 0.93. Synonymous variants: 328 observed, 286.45 expected, observed/expected ratio (o/e) 1.15, 90% interval 1.04 to 1.25.
Homologues: Orthologues: chimpanzee ZNF358 (98% identical), macaque ZNF358 (97% identical), dog ZNF358 (88% identical), pig ZNF358 (87% identical), guinea pig ZNF358 (87% identical), mouse Zfp358 (83% identical), rabbit ZNF358 (81% identical), rat Zfp358 (76% identical). Paralogues in human: ZNF850 (26% identical), ZNF668 (21% identical), PRDM5 (19% identical), ZNF579 (15% identical).
Diseases named in the same sentence as ZNF358 in open-access papers:
ZNF358 is named in the same sentence as 1 disease in open-access papers, as found by Europe PMC text mining. Sharing a sentence is not in itself a finding about the gene and the disease.
ZNF358 shares sentences with these, for which no sentence is quoted: meningioma (1 paper).